XBP1 (X-box binding protein 1)
Diseases named in the same sentence as XBP1 in open-access papers (continued):
Sharing a sentence is not in itself a finding about the gene and the disease.
blood cancers (1 paper, 2025). "Of note, the FDA-approved anticancer drug sunitinib inhibits IRE1α autophosphorylation, diminishing XBP1 splicing in blood cancer cells treated with an ER stress inducer." (PMID 41301006, 2025). "FDA-approved for blood cancers; inhibits IRE1α autophosphorylation, reducing XBP1 splicing in blood cancer cells." (PMID 41301006, 2025).
XBP1 also shares sentences with these, for which no sentence is quoted: liver (4 papers); autoimmune disease (3); bladder cancer (3); esophageal cancer (3); Parkinson (3); rhabdomyosarcoma (3); cataract (2); chronic kidney disease (2); chronic periodontitis (2); congenital cataracts (2); Frontotemporal lobar degeneration (2); helminth infection (2); Impaired glucose tolerance (2); Intestinal inflammation (2); kidney carcinoma (2); prostate adenocarcinoma (2); testicular germ cell tumor (2); Ureteral obstruction (2); uterine corpus endometrial carcinoma (2); abscesses (1); adenoma (1); alcoholic fatty liver disease (1); allergic rhinitis (1); Allergy (1); aneurysm (1); ankylosing spondylitis (1); Arthralgia (1); atrial fibrillation (1); B-cell acute lymphoblastic leukemia (1); brain cancer (1).
A further 63 diseases each share a sentence with XBP1 in 1 paper.